STAT3 (signal transducer and activator of transcription 3)
Diseases named in the same sentence as STAT3 in open-access papers (continued):
Sharing a sentence is not in itself a finding about the gene and the disease.
cancer (continued). "It is reported that when cancer-related inflammatory cytokine interleukin (IL)-6 binds to its receptor, STAT3 would be activated." (PMID 34257541, 2021). "Adiponectin inhibits the proliferation of cancer cells by downregulating STAT3 and upregulating SOCS3." (PMID 34588926, 2021). "In this review, we focus on the effects of inflammation on cancer stem cells, particularly the role of signaling pathways such as NF-κB pathway, STAT3 pathway and Smad pathway involved in regulating epigenetic changes." (PMID 34722553, 2021). "This study shows that circFAT1 controls cancer stemness and immune evasion by regulating STAT3 activation." (PMID 34258151, 2021). "Inhibition of STAT3 activity by small molecules can impede the growth of cancer cells, making STAT3 an important target in anticancer drug discovery." (PMID 34299488, 2021). "In human cancer cells, the activation of STAT-3 contributes to persistent STAT-3 target gene activation, which can stimulate some pathways like angiogenesis, apoptosis prevention, and cell growth, thereby driving tumorigenesis." (PMID 33987085, 2021). "Second, the monoclonal antibody Tocilizumab, already used in clinic to inhibit IL-6R, prevented STAT3 activation in cancer cells." (PMID 34440697, 2021). "Previous studies have indicated that IL-6 drives many of the expression of cancer ‘hallmarks’ through the downstream activation of the JAK/STAT3 signaling pathway." (PMID 33919077, 2021). "STAT3 signaling was found to be an important pathway involved in the transcriptional regulation of Sox2 to promote the stemness of cancer cells." (PMID 33456560, 2021). "STAT3 signaling is crucial for the signal transduction cascade, in which cancer cells sense and adapt to a variety of environmental stimuli." (PMID 34179090, 2021). "STAT3 inhibitors can inhibit the proliferation and development of cancers by blocking IL-6/STAT3 signaling, suppressing cancer cells proliferation and promoting apoptosis." (PMID 34976809, 2021). "Signal transducer and activator of transcription 3 (STAT3), a transcription factor for survival and proliferation, is essential to survival and maintains tumorigenesis in many cancers." (PMID 34502158, 2021). "Signal transducer and activator of transcription 3 (STAT3) is overexpressed in various cancer types and modulates various cellular processes like proliferation, apoptosis, and differentiation, which makes it an attractive anticancer target." (PMID 34760885, 2021). "As STAT3 is a central driver of cell survival and inhibition of apoptosis in cancer, we determined the impact of CD109 silencing on cell viability." (PMID 33986188, 2021). "In cancer, increased levels of IL-6 result in increased activation of Jak-Stat3 pathway, which correlates with poor prognosis." (PMID 34376733, 2021). "The positive feedback loop demonstrated here suggests that IL-6/STAT3 play critical roles in the initiation and promotion of cancer metastasis." (PMID 33500736, 2021). "The central role of STAT3 in the development of a large number of tumors makes this protein an attractive target for studies of cancer therapy." (PMID 34440160, 2021). "Of note, preclinical studies show that long noncoding RNA FOXD2-AS1 regulates therapeutic resistance in laryngeal squamous cell carcinoma (LSCC) by acting as an upstream activator of STAT3, which is essential to maintain cancer stemness." (PMID 33718169, 2021). "Intriguingly, we found that circFAT1 controlled cancer stemness and antitumor immunity through STAT3 activation, providing important insights into immune evasion of CSCs in HNSCC." (PMID 34258151, 2021). "STAT3 plays a critical role in many pathophysiological processes, including cancer cell proliferation, anti-apoptosis, and metastasis." (PMID 34301920, 2021). "STAT3 is also important to cell activities, such as proliferation, apoptosis and is a prominent target for cancer therapy." (PMID 34179090, 2021).
cancer (continued). "IL6/STAT3 pathway had been demonstrated that played a contributing factor for multidrug resistance in cancer." (PMID 34373835, 2021). "EGFR-Src-STAT3 signaling is also considered as an important pathway in tumorigenesis in various cancer types." (PMID 33925065, 2021). "The STAT3 transcription factor has been extensively studied as a transcriptional regulator in many diseases, including cancers." (PMID 34948097, 2021). "It would be of great significance to investigate the effects of PRMT5 inhibitors in cancer types with aberrantly hyperactivated STAT3 signaling." (PMID 34026434, 2021). "The IL-6/JAK/STAT3 signaling pathway is aberrantly hyperactivated in patients with hematopoietic malignancies or solid tumors in cancer patients." (PMID 34638439, 2021). "STAT3 signaling is involved in the regulation of metastasis, the transition of cancer stem cells, and chemoresistance of cancer by epithelial-mesenchymal transition." (PMID 34376200, 2021). "Molecular mechanisms dictating the cancer cell-intrinsic responsiveness to nintedanib, such as STAT3 activation and lysosomal trapping, are amenable to pharmacological intervention with silibinin." (PMID 34439322, 2021). "Inhibiting the BRAF(V600E) or STAT3 pathway or modulating cancer cell autophagy was also reported to sensitize cancer cells to NK cell cytotoxicity." (PMID 34072732, 2021). "Previous studies reported STAT3 activity favors anoikis resistance and metastasis in cancer 21-23, 28, however, the role of STAT3 in mediating anoikis resistance and oncogenic phenotypes in cancer is yet to be fully understood." (PMID 34234852, 2021). "The key molecular links between inflammation and cancer involve the canonical nuclear factor kappa-light-chain-enhancer of activated B cells (NF-kB) activation and Signal transducer and activator of transcription 3 (STAT3) pathways." (PMID 34367064, 2021). "Preclinical evaluations demonstrated that AZD9150 decreased the expression of STAT3 and exhibited prominent antitumor effects in several preclinical cancer models of lymphoma and LC." (PMID 33740988, 2021). "STAT3 has been found to be activated inappropriately in a wide range of human cancers, including CRC." (PMID 34638550, 2021). "Previous studies have shown that STAT3 activation subsequently increased c-myc, Bcl-2, and Mcl-1 transcription, thereby inducing cancer cell proliferation and survival." (PMID 33731185, 2021). "Bozec and associates reported reverse correlation expression of miR-223 and STAT3 in cancer cells; STAT3 is one of the key signaling factors in malignant cell proliferation." (PMID 33430952, 2021). "Next, from the CCLE database, TINCR expression was found to be positively correlated with STAT3 expression in human cancer cells." (PMID 33446634, 2021). "To develop a more successful treatment for cancer, we have done much work on finding an effective STAT3 inhibitor." (PMID 33259114, 2021). "In other study, DHTS has been shown to inhibit cancer stem cells (CSCs) in TNBC cell line i.e. MDA-MB-231 by activation of NOX5 mediated ROS/Stat3/IL-6 pathway." (PMID 34319041, 2021). "Targeting STAT3 activity is a promising strategy both in combinational and multimodal approaches in cancer therapy." (PMID 34884773, 2021). "Most direct STAT3 inhibitors (STAT3i) have yet to enter clinical evaluation, early-phase clinical trials have produced mixed results with STAT3-targeted cancer therapies and, despite decades of research, very few FDA-approved STAT3i are available." (PMID 35056076, 2021). "The newly identified cancer-promoting role of STAT3 in mitochondria further emphasizes the importance of targeting STAT3." (PMID 34277607, 2021). "The expression of apoptosis-, growth- and metastasis-related proteins, such as Bcl-xL, Bcl-2, VEGF, Src, CXCR4, and MMP2/9 were also regulated by phosphorylated STAT3 forms, thus promoting the growth, development and inhibition apoptosis of cancer cells." (PMID 34976809, 2021).
cancer (continued). "The STAT3/hnRNPA1 pathway can partially explain the up‐regulation of miR‐27b‐3p in EMT cancer cell‐derived exosomes." (PMID 34936736, 2021). "circ-ZNF124 negates the miR-337-3p-mediated repression of JAK2/STAT3, and the consequent activation of this pathway increases cancer cell growth, migration, and colony formation abilities." (PMID 34205978, 2021). "In tumorigenesis, STAT3 is highly involved in immune checkpoints that maintain tolerance in the immune system against cancer cells." (PMID 34298665, 2021). "Peroxiredoxins are involved in a variety of signaling pathways, such as the NF-κB signaling, STAT3, Wnt/β-catenin and MAPK kinase pathways, which are closely associated with cancer development." (PMID 33819194, 2021). "Many genes or proteins can have dual roles in biological processes, such as the overexpression of STAT3 in several cancer cells." (PMID 33902757, 2021). "STAT3 activation is abnormal in human cancers, such as OS, and transformed cell lines indicating the potential role of STAT3 in oncogenesis." (PMID 33382511, 2021). "Signal transducer and activator of transcription (STAT) proteins, i.e., STAT3, are potential targets for cancer therapy." (PMID 33896365, 2021). "Taking HCC as an example, in cancer cells, miR-124 targets transcription activator STAT3 to perform induction of apoptosis and inhibition of proliferation, thus suppressing the growth of HCC." (PMID 34115554, 2021). "The intense investigations have identified multiple roles of STAT3 in cancer initiation and progression." (PMID 34638338, 2021). "Inhibition of STAT3 signal by Static, a synthetic inhibitor of STAT3, increased the sensitivity of cancer cells to gefitinib." (PMID 33392396, 2021). "Janus kinase 2 (JAK2) and signal transducer and activator of transcription 3 (STAT3) signaling is an essential pathway in human cancers, as well as CSCs, acting by regulating inflammatory cytokines such as interleukin (IL)-6." (PMID 33805840, 2021). "The negative regulation of ERK1/2 by STAT3, that was observed here in the course of Lovastatin treatment, has been recently reported in other cancer cell type." (PMID 33987937, 2021). "IL-6 can be an activator to induce the phosphorylation of STAT3, so in order to further explore the antitumor mechanism, we treated cancer cells with IL-6 after the combination therapy." (PMID 34900688, 2021). "Then we asked if STAT3 signaling affects V-ATPase expression observed in these cancer cells grown in anchorage-independent conditions." (PMID 34234852, 2021). "Specifically, it has been reported that STAT3 regulates the glucose metabolism through increasing the HK2 expression in cancer cells." (PMID 34326684, 2021). "Activation of STAT3 via Y705-phosphorylation broadly exists in cancers, and its tumorigenic role has been widely recognized." (PMID 34076564, 2021). "AKT and ERK are key mediators in regulating the survival and proliferation of cancer cells, whereas STAT3 is a transcription factor involved in cell survival and apoptosis." (PMID 34721022, 2021). "As the nuclear localization of p-STAT3 mediates the transcription of downstream genes for cancer proliferation, the localization of p-STAT3 in the cytosol was examined by IF staining in H460 cells." (PMID 34445110, 2021). "NF-κB and STAT3 regulate the inflammation, survival, proliferation, invasion, angiogenesis, and metastatic potential of cancers cells." (PMID 33917793, 2021). "The overexpression of STAT3 targeted genes due to its persistent activation in cancers provides enormous growth potential to the cancer cells and encourages the advancement of the disease." (PMID 34771643, 2021). "The detailed mechanism was elucidated that activating PPARγ by Alp treatment resulted in the downregulated phosphorylation of NF-κB (p65 subunit) and STAT3, two crucial regulatory pathways of cancer cachexia." (PMID 34093209, 2021).
cancer (continued). "The interconnection of signaling pathways such as Nrf2, NF-κB, and STAT3, and aberrations in their activation mechanisms, make it possible to use them as a target in cancer cells for potential chemotherapeutic and/or chemopreventive compounds." (PMID 34443544, 2021). "The study reported here supports a role for elevated S100B levels in suppressing IL6/STAT3 signaling providing additional evidence of S100B in supporting cancer." (PMID 34411141, 2021). "Transcriptional factor STAT3 can also been induced and shown to directly or indirectly upregulate the expression of genes that are required for cancer progression." (PMID 34154618, 2021). "Compelling evidence demonstrates that STAT3 impacts the invasion and migration of cancer cells via EMT." (PMID 34876150, 2021). "The aberrant activation of a signal transducer and activator of transcription 3 (STAT3) restrains type I interferon (IFN) α/β-induced antiviral responses and is associated with the development of cancer." (PMID 33805945, 2021). "Among these genes, we selected Snai2, also named Slug, as a possible effector molecule of CXCR4/STAT3 signaling, since several reports have shown the role of Slug in IR resistance of various cancer cells." (PMID 33414415, 2021). "An ongoing clinical trial explores the STAT3/NF-κB/polycytosine kinase inhibitor IMX-110 in combination with low-dose doxorubicin (NCT03382340) to kill cancer cells." (PMID 34683963, 2021). "IL-6 can regulate the crosstalk between CSCs and cancer cells through constitutive activation of Stat3, and Stat3 regulates the expression of Oct3/4, which is a major reprogramming factor known to induce the expression of various stemness genes." (PMID 33804152, 2021). "STAT3 is constitutively activated in several cancers and is thought to play a critical role in tumor growth and metastasis." (PMID 33525518, 2021). "Depletion of PDS5B in cancer cells induces secretion of interleukin-6 (IL-6), which binds to its receptor and in turn activates intracellular STAT3." (PMID 34070827, 2021). "Gal‐3 increased PD‐L1 expression via the upregulation of STAT3 phosphorylation, and administration of a Gal‐3 inhibitor enhanced the effect of PD‐L1 blockade on the cytotoxic activity of T cells against cancer cells in vitro." (PMID 33455075, 2021). "It suppresses mitochondrial electron transport chain complex activities, affects several signaling pathways such as JAK/STAT3 and Wnt, and inhibits cancer cell proliferation." (PMID 34950627, 2021). "To date, a vast number of agents ranging from antisense oligonucleotides and repurposed drugs, JAK1/2 to direct STAT3 inhibitors have been the subject of investigation in numerous cancers." (PMID 33498872, 2021). "The expression of SLUG in GBM was found to be induced by the activation of JAK/STAT3 axis in order to activate cancer cell motility and invasion." (PMID 34141616, 2021). "Five of these signatures, including IFNα, IFNγ, STAT3, TGFβ and TNFα pathway signatures, are cancer immunity-related." (PMID 33767579, 2021). "A recent study reported the downregulation of miR-519a-3p in GBM and its role in enhancing chemosensitivity and promoting cancer cell autophagy via targeting the STAT3/B cell lymphoma 2 (Bcl2) signaling." (PMID 34867700, 2021). "Corroborating the apoptosis results of the STAT3 inhibitor S3I-201 assay, the senescence-like CAF CM reduced IR-induced apoptosis of cancer cells, and knockdown of STAT3 reversed this phenomenon." (PMID 34877934, 2021). "From our results, we first identified the roles and underlying mechanisms of MSI1 and miR-671-5p in GBM, which regulate radioresistance by STAT3 inhibition and cancer migration and CSC function by TRAF2 suppression." (PMID 35052701, 2021). "Our data are in agreement with previous reports showing that p-STAT3-high cell lines from various cancer models secrete higher levels of IL-6 while p-STAT3-low cancer cell lines demonstrate low levels of IL-6 production." (PMID 34956861, 2021).
cancer (continued). "Taken together, these findings illustrate that abnormal expression of circFAT1 controls cancer stemness and immune evasion by promoting STAT3 activation." (PMID 34258151, 2021). "In this regard, the amplification of FGFR1 in cancer cells was shown to trigger the recruitment and activation of STAT3." (PMID 33535617, 2021). "Here, we show that the PERK-JAK/STAT3 pathway can operate in certain cancer cell lines, adding to the molecular repertoire of ER stress-induced intra- and intercellular responses." (PMID 34725321, 2021). "Although STAT3 is often hyperactivated in cancer, it is essential for normal development and physiology." (PMID 33986188, 2021). "STAT3 is a transcription factor and plays a critical role in tumorigenesis, which makes it as a potential molecular target in cancer therapy." (PMID 33753770, 2021). "In this study, we aim to reveal the role of HMGA2 in TNBC biology and demonstrate a link between HMGA2-mediated cancer phenotypes and the regulation of NF-kB/IL-6/STAT3 signaling." (PMID 34680349, 2021). "It is well known that JAK2/STAT3 signaling pathway is constitutively activated in most primary malignant cancers and its activation rate is positively related with tumor grade." (PMID 33800266, 2021). "Previous research reported that JAK1/STAT3 signalling pathway was regulated by several growth factors, and subsequently contributes to cancer progression." (PMID 33523587, 2021). "The overactivation of STAT3 is associated with decreased survival and a high risk of recurrence of HCC and many other types of cancer." (PMID 33805945, 2021). "↓ mTOR and STAT3 pathway signalling in response to a CDK4/6 inhibitor repressing the stemness of HNSCC cancer cells." (PMID 34137158, 2021). "The recently discovered cancer‐promoting functions of STAT3 further emphasize the importance of targeting STAT3 activities related to the mitochondria, epigenetic regulation, cancer stem cells, pre‐metastatic niches and more." (PMID 33259114, 2021). "Our in vitro data suggest that the IL-6 and JAK2/STAT3 pathways suppress STING function in cancer cells." (PMID 33790360, 2021). "TrkA-mediated phosphorylation and activation of STAT3 represents a novel mechanism by which STAT3 is activated in human cancers." (PMID 34066153, 2021). "Studies have indicated that activating the p-STAT3/bcl-2 signaling pathway suppresses apoptosis in several cancers." (PMID 34170850, 2021). "It has been reported that attenuated STAT3 activation results in inhibition of cell proliferation and apoptosis induction in many cancer cells." (PMID 34502158, 2021). "Persistent activation of STAT3 also contributes to tumorigenesis by upregulating the transcription of genes that control cancer cell survival (e.g., cyclins and c-MYC), resistance to apoptosis (e.g., BCL2, MCL1), and cell cycle activation." (PMID 34944848, 2021). "The exposure of fibroblasts to chemotherapy also resulted in a higher secretion of IL-11, which activated STAT3 signalling in cancer cells and drove the upregulation of anti-apoptotic pathways." (PMID 34298736, 2021). "Q-PCR was used to reveal that the transcriptional levels of STAT3-supporting cancer cell-intrinsic hallmarks, including BCL2, MMP9, HIF-1α and PIM1, were all decreased with SPATS2 knockdown in both MHCC-97H and HCC-LM3 cell lines." (PMID 33391405, 2021). "JAK2 functions as a prototypical kinase that phosphorylates STAT3, which activates the JAK2/STAT3 signaling pathway and promotes tumorigenesis and progression in several cancer types." (PMID 34496932, 2021). "Recent evidence demonstrates that STAT3 and PD-L1 are involved in a variety of biological processes, such as cancer growth, metastasis and modulation of the immune microenvironment in cancer cells." (PMID 34440920, 2021).